INS (insulin)
Diseases named in the same sentence as INS in open-access papers (continued):
Sharing a sentence is not in itself a finding about the gene and the disease.
Insulin resistance (continued). "Our finding concerning insulin is also consistent with a previous study showing insulin resistance associated with higher BCAAs52, possibly via decreased BCAA metabolism due to impaired insulin action." (PMID 38459184, 2024). "In those with insulin resistance, more insulin is required to manage elevated blood glucose levels, which also leads to impaired insulin action in other tissues, including the endometrium." (PMID 38310251, 2024). "What counts is that researchers found that RSV restores the phosphorylation levels of AKT and PI3K in the liver of insulin resistance mice, which are involved in the insulin signaling pathway and were decreased by a high-fat diet." (PMID 38799166, 2024). "Total cholesterol, low-density lipoprotein, high-density lipoprotein, triglycerides, glucose, insulin, homeostatic model assessment for insulin resistance, and transaminases worsened during the lockdown (glucose: p = 0.0007; p < 0.0001 for the others)." (PMID 38802382, 2024). "There was no multicollinearity between the independent variables used in each model (Variance Inflation Factor, VIF < 2) (age, sex, TIV, BMI and fasting plasma glucose, fasting plasma insulin or insulin resistance)." (PMID 39085221, 2024). "To examine if HF affected insulin resistance, we subjected the same cohort of mice to insulin tolerance tests and monitored glucose clearance over time." (PMID 39150520, 2024). "In line with the results of our study, human studies have also observed the improvement of average insulin levels and insulin resistance index (HOMA-IR or HOMA-β) in the group supplemented with GSE." (PMID 38755622, 2024). "Thirdly, insulin resistance reduces insulin sensitivity in the liver and muscle tissue, thereby impeding insulin utilization and glucose uptake." (PMID 39758345, 2024). "AHB, LGPC, oleic acid, and insulin have been utilized as the foundation for an insulin resistance assay since all four are recognized as biomarkers of insulin sensitivity." (PMID 38612284, 2024). "These mice also exhibited insulin resistance despite being lean, whereas lipin 1–overexpressing mice had increased adiposity yet were insulin sensitive." (PMID 39405118, 2024). "Insulin resistance is a key factor in metabolic disorders, and it has been shown that miRNAs can regulate the expression of the insulin pathway and insulin resistance." (PMID 38262955, 2024). "Major changes in glucose metabolism occur throughout pregnancy and consist of higher insulin resistance and a compensatory increase in insulin secretion to maintain glucose homeostasis." (PMID 39330515, 2024). "Insulin resistance serves as the central feature of MS, reducing the body’s sensitivity to insulin and leading to glucose metabolism dysfunction." (PMID 38792681, 2024). "South Asians tend to have higher insulin resistance, lower beta-cell insulin secretion, and more ectopic fat in the liver than age- and BMI-matched white Europeans." (PMID 38786765, 2024). "A recent meta-analysis of randomized controlled trials demonstrated that vitamin D supplementation in patients with type 2 DM can lead to improvements in HbA1c, insulin resistance, and insulin secretion during short-term interventions." (PMID 39857652, 2024). "Type II diabetes is also characterized by two significant conditions resulting from defective insulin secretion or reduced insulin sensitivity (insulin resistance)." (PMID 38658923, 2024). "In myotubes treated with palmitate, WEPE prevented palmitate-induced insulin resistance by enhancing insulin-mediated glucose uptake and AKT phosphorylation." (PMID 39095777, 2024). "Obesity can lead to insulin resistance, a condition where the body's cells become less responsive to insulin." (PMID 39310400, 2024). "Insulin resistance, defined as peripheral tissue’s failure to respond to insulin, is a key feature of metabolic syndrome and an increasing risk factor for BMD loss." (PMID 39744182, 2024).
Insulin resistance (continued). "Postpartum obese cows, often exhibit higher NEFA, elevated NEFA can hinder downstream insulin signaling events and worsen insulin resistance." (PMID 39881718, 2024). "The corresponding insulin resistance in hyperinsulinemia further aggravates the situation by demanding higher insulin levels for maintaining glucose balance." (PMID 38256276, 2024). "In obesity, with peripheral insulin resistance and, therefore, decreased responsiveness to insulin-mediated glucose disposal or adipose tissue lipolysis, insulin concentrations increase and IGFBP-1 is suppressed." (PMID 39595651, 2024). "Metformin decreases insulin resistance and lowers circulating insulin levels, leading to decreased signalling on insulin-like growth factor receptors and insulin receptors." (PMID 39588310, 2024). "It is likely that the relapse occurs due to increased demand for insulin production because of increased insulin resistance that can arise with age, especially during puberty." (PMID 40302951, 2024). "The development of insulin resistance initially leads to higher plasma insulin levels to overcome the resistance state." (PMID 36795085, 2024). "When insulin resistance is present, the postprandial glucose response is typically higher and more prolonged than in those with healthy insulin sensitivity." (PMID 38201992, 2024). "Insufficient insulin signaling and insulin resistance, observed in prediabetic or diabetic states, have been associated with neurodegenerative diseases." (PMID 39110798, 2024). "Obesity is frequently accompanied by insulin resistance, where cells become less responsive to insulin." (PMID 38807790, 2024). "Obesity-induced neuroinflammation contributes to insulin resistance, and promotion of insulin signaling attenuates neuroinflammation and neurodegeneration." (PMID 39897964, 2024). "According to the results of the present study, the sleep quality of adolescents with obesity is significantly and inversely related to their BMI, fasting insulin levels, and the insulin resistance HOMA-IR index." (PMID 39594947, 2024). "It is upregulated in white adipose tissue of type 2 diabetes patients and negatively correlated with insulin sensitivity in insulin‐resistance individuals." (PMID 38838088, 2024). "Studies have shown that SOCS3 is a vital risk factor for T2DM as it can inhibit insulin signaling and JAK/STAT signal channel conduction, lead to insulin resistance and higher levels of blood glucose." (PMID 39596180, 2024). "TNF-α directly contributes to insulin resistance by activating stress kinases, thus blocking insulin signal transduction." (PMID 38683749, 2024). "Meanwhile, type II diabetes is characterised by insulin resistance and impaired insulin secretion, often regarded as a metabolic disorder due to pancreatic β-cells dysfunction." (PMID 38770527, 2024). "T2D is characterized by the inability of insulin-sensitive tissues to respond to insulin (insulin resistance) and a gradual decrease in insulin production due to a reduction in beta-cell function and number in the pancreas." (PMID 39201524, 2024). "In type 2 DM, the HGF-Met system improves insulin sensitivity in mouse models of insulin resistance, likely through direct interactions between the Met receptor and the insulin receptor, affecting hepatic glucose management." (PMID 38654922, 2024). "Although GDM is generally characterized by increased insulin resistance and reduced insulin secretion, considerable heterogeneity exists." (PMID 39081793, 2024). "Concentrations of fasting insulin and the homeostasis model assessment for insulin resistance were used as indicators of insulin resistance." (PMID 39347227, 2024). "Insulin levels increased in both groups, consistent with the development of insulin resistance during the progression of obesity." (PMID 39019114, 2024).
Insulin resistance (continued). "Hyperpolarization of macrophages results in excessive production of inflammatory factors, disrupts the expression of crucial proteins in the insulin signaling pathway, and significantly contributes to the development of hepatic insulin resistance." (PMID 39179999, 2024). "Insulin resistance is physiologically defined as a state in which the responsiveness of insulin‐target tissues to high physiological insulin levels is reduced." (PMID 39465505, 2024). "This impairs the IRS/phosphatidylinositol 3-kinase (PI3K) signaling pathway, hindering insulin signal transduction and contributing to insulin resistance." (PMID 39458502, 2024). "Over time, frequent insulin spikes, particularly from refined sugars and rapidly digestible carbohydrates such as sugary products and white bread, can lead to insulin resistance." (PMID 39458518, 2024). "The etiology of insulin resistance is multifactorial and can include defects in the insulin signaling pathway preventing proper insulin-stimulated glucose uptake through glucose transporter 4 (GLUT-4)." (PMID 38791018, 2024). "The first mechanism is supported by the report that anti-TNFα treatment ameliorates insulin sensitivity and also by the findings that TNFα-activated JNK directly phosphorylates IRS1/2, causing insulin resistance." (PMID 38397480, 2024). "In other words, inflammation can alter endothelial permeability and decrease peripheral blood flow, thereby limiting insulin delivery and promoting insulin resistance." (PMID 38276133, 2024). "Glucose tolerance test and insulin tolerance test data showed that insulin resistance is increased in Cbfa2t3−/− mice compared to Cbfa2t3+/+ mice." (PMID 38786053, 2024). "In animal models, resistance training has been shown to improve insulin resistance and glucose tolerance, reduce adipocyte size, and activate insulin pathways in skeletal muscle." (PMID 39334887, 2024). "The homeostatic insulin resistance, the glucose–insulin ratio, and the quantitative insulin sensitivity check (QUICKI) were calculated using mathematical models." (PMID 39408354, 2024). "His bloodwork revealed hemoglobin A1C of 5 (normal, <5.7), C-peptide 2.14 (normal, 0.8-1.8), fasting insulin 13.1 (normal, 5-12), and fasting glucose 99 (normal, 70-100), with insulin resistance score 3.2 (normal, <2), indicative of insulin resistance." (PMID 39135763, 2024). "Another final consideration is about irisin’s potential to enhance insulin signaling, a feature that suggests its relevance in addressing insulin resistance-related conditions, such as AD." (PMID 39769243, 2024). "Insulin resistance reduces the sensitivity of organs like the liver and adipose tissue to insulin, resulting in heightened fatty acid synthesis within the liver." (PMID 39777076, 2024). "Once this feedback is disrupted, the antagonistic effect of leptin on insulin production affects signal transduction pathways following insulin–receptor binding, resulting in the development of insulin resistance." (PMID 40302954, 2024). "Although the primary etiologic event for hyperinsulinemia is not explicit, OLETF demonstrates pancreatic β-cell dysfunction by 16 wk marked by insulin resistance and impaired insulin secretion." (PMID 37899754, 2024). "Insulin resistance, characterized by an abnormal biological response to insulin, alone as a pre-diabetic state or as type 2 diabetes mellitus (T2DM) and obesity syndromes, is a risk factor for metabolic complications and cognitive dysfunction." (PMID 39000130, 2024). "This condition is an early compensatory response to insulin resistance, where the pancreas produces more insulin to overcome reduced insulin sensitivity." (PMID 39290325, 2024). "Individuals with insulin resistance are characterized by the inability to respond to secreted insulin, which can be at normal or high levels." (PMID 37938877, 2024).
Insulin resistance (continued). "Excessive lipolysis in white adipose tissue (WAT) leads to insulin resistance (IR) and ectopic fat accumulation in insulin-sensitive tissues." (PMID 38470490, 2024). "T2D is characterized by insulin resistance, translated by a defective tissue response to physiological levels of insulin, followed by impaired insulin secretion from pancreatic β cells." (PMID 39518420, 2024). "Given the well-established role of obesity and insulin resistance in Metabolic Syndrome development, we calculated correlations between the 18 lipids exhibiting differential expression and key MetS components: BMI, insulin, and HOMA-IR." (PMID 38932852, 2024). "Insulin resistance is a condition in which the insulin circulating in the blood is unable to properly stimulate glucose uptake and/or use by insulin-sensitive organs and tissues." (PMID 38792339, 2024). "Fasting hyperglycemia is a sign of insulin resistance, inadequate insulin production, or a combination of both." (PMID 38956678, 2024). "Some other pharmacological indexes, such as serum insulin, glucose, and homeostasis model assessment-insulin resistance (HOMA-IR), were also recorded." (PMID 38313314, 2024). "Hyperglycemia results from a combination of insulin resistance and insufficient insulin secretion, which can lead to vascular damage, neuropathy, and nephropathy if persistent." (PMID 38792681, 2024). "Insulin sensitivity was assessed using a Homeostatic Model Assessment of Insulin Resistance (HOMA-IR) and C-reactive protein (CRP) levels were used as a proxy for inflammation." (PMID 38337673, 2024). "In the presence of elevated inflammation, the capacity of insulin to regulate metabolism is compromised, which resulted in the pathogenesis of insulin resistance and cardiovascular disorders." (PMID 38755663, 2024). "Although fructose exposure during pregnancy has been shown to hyperinsulinemia, impaired insulin signaling, and low adiponectin levels, finally insulin resistance has been reported only in male offspring." (PMID 39334462, 2024). "Another explanation for selective insulin resistance in the liver suggests the different sensitivities of insulin-induced activation of sterol regulatory element-binding protein 1c (SREBP-1c) and suppression of gluconeogenesis." (PMID 38397072, 2024). "In the present study, we used mediation analyses to demonstrate that the association between a higher IMAT and a lower eGFR in SLE patients was mediated in part by a reduction in the patients’ sensitivity to insulin (insulin resistance)." (PMID 38886276, 2024). "Under conditions of insulin resistance and cellular stress, α-cells can regulate insulin secretion by producing GLP-1, thereby compensating for the increased functional demands of β-cells." (PMID 39598478, 2024). "For T2D patients, although the primary issue is insulin resistance, the use of insulin or certain oral hypoglycaemic drugs can also lead to hypoglycaemia." (PMID 39238070, 2024). "For example, lncRNA MEG3 has been shown to increase gluconeogenesis and impair insulin-stimulated glycogen synthesis, promoting hepatic insulin resistance." (PMID 39335472, 2024). "After years of insulin resistance and hyperinsulinemia, the beta-cells are malfunctioned and secrete lower insulin amounts." (PMID 39335530, 2024). "TNF-alpha (TNFα) links obesity and insulin resistance by interfering with the early stages of insulin signaling." (PMID 39766314, 2024). "Insulin resistance (IR) is a state of reduced sensitivity and responsiveness of the body to insulin, usually occurring in the prediabetic and diabetic stages." (PMID 39346096, 2024). "In patients with PCOS, insulin resistance is characterized by a reduced ability of these peripheral tissues to respond to normal or elevated concentrations of insulin." (PMID 39459443, 2024).
Insulin resistance (continued). "Clinically, insulin resistance refers to the inability of a known amount of endogenous or exogenous insulin to raise an individual’s absorption and utilization of glucose to the same extent as it does in the normal population." (PMID 38463431, 2024). "T2DM is pathologically characterized by insulin resistance and early hyperinsulinemia, subsequently progressing to a decline in insulin production within pancreatic β cells." (PMID 38254542, 2024). "Animal studies suggest that resistin has significant activities on insulin action, potentially linking obesity with insulin resistance." (PMID 38474226, 2024). "Preclinical studies in mice have shown that both genetic modulation and protein concentrations of PPARα and PGC-1α are impaired in insulin resistance conditions, leading to an impairment of the insulin–cardiac axis." (PMID 39125938, 2024). "Insulin resistance refers to a diminished response of tissues to insulin stimulation and is considered a key factor in glucose and lipid metabolism." (PMID 38404616, 2024). "There was a subfield specific effect of fasting insulin and insulin resistance in FEP at the follow-up time point (subfield by insulin F3.4,72 = 3.73, p = 0.011; subfield by insulin resistance F3.4,71 = 3.45, p = 0.017)." (PMID 39085221, 2024). "Increased lipid deposition in tissues is closely associated with insulin resistance, and CAMK4 enhances insulin sensitivity and indirectly modulates lipid metabolism." (PMID 38203803, 2024). "Insulin resistance in the heart disrupts insulin signalling‐mediated substrate utilization, increasing the likelihood of cardiac insufficiency." (PMID 38494853, 2024). "Although GDM women generally show higher absolute insulin levels, they are insufficient to overcome the prevailing insulin resistance." (PMID 39389786, 2024). "Systemic insulin resistance impedes glucose uptake, and hepatic insulin resistance disrupts insulin’s suppression of hepatic glucose production while stimulating lipogenesis." (PMID 39451562, 2024). "In this scenario, the role played by the inflammatory environment in inducing additional insulin resistance seemed to explain worsened insulin sensitivity due to pyometra compared with the isolated diestrus influences." (PMID 38539988, 2024). "Fasting insulin and homeostatic model assessment for insulin resistance were reduced after 12 weeks of cinnamon intake." (PMID 38671840, 2024). "The importance of impaired insulin release and insulin resistance in the pathogenesis of T2D is well known and has been evaluated in numerous prior studies." (PMID 38957656, 2024). "Meanwhile both doses can significantly improve insulin resistance, and increased insulin sensitivity index." (PMID 39179999, 2024). "Insulin resistance (IR), denoting diminished sensitivity and responsiveness to the physiological actions of insulin, has been duly acknowledged as a defining feature of type 2 diabetes." (PMID 38216931, 2024). "The connection between obesity and elevated insulin levels leads to an increased insulin resistance in peripheral tissues." (PMID 39457167, 2024). "High circulating insulin levels and insulin resistance are known to contribute to cognitive impairment in the old and oldest-old." (PMID 38542318, 2024). "Our results demonstrated that feeding adult flies on HSD led to insulin resistance, a physiological condition characterized by reduced tissue responsiveness to insulin and low glucose uptake." (PMID 38916917, 2024). "Insulin resistance refers to the inability of the peripheral and central tissues of the body to respond to insulin and effectively regulate blood sugar levels." (PMID 38818523, 2024). "Our research work presents a groundbreaking finding, illustrating that the reduction of BVR-A protein levels is sufficient to compromise the insulin-mediated response, reminiscent of a state akin to insulin resistance." (PMID 38843768, 2024).